SOCS1 (suppressor of cytokine signaling 1)
Diseases named in the same sentence as SOCS1 in open-access papers (continued):
Sharing a sentence is not in itself a finding about the gene and the disease.
leukemia (25 papers, 2005 to 2024). A malignant (clonal) hematologic disorder, involving hematopoietic stem cells and characterized by the presence of primitive or atypical myeloid or lymphoid cells in the bone marrow and the blood. "The increased SOCS1 level in the bone marrow of AML patients was closely associated with advanced age, mutations in FLT3-ITD, NPM1, and DNMT3A, and SOCS1 overexpression in zebrafish mimic leukemia phenotype." (PMID 38161382, 2023). "Several genomic single nucleotide polymorphisms within the locus of SOCS1 are associated with the dysfunction of SOCS1 in leukemia." (PMID 28228755, 2017). "In similarity, our findings revealed that the cell proliferation inhibition of HL60 leukemia cells was associated with a significant re-expression of SHP-1, SOCS-1, and SOCS-3 genes after exposure to 2 μM TQ." (PMID 33773553, 2021). "Taken together, the findings of the present study indicate that TQ induced cell proliferation inhibition of HL60 leukemia cells with a cell cycle arrest in early stages, and apoptosis induction associated with re-expression of SHP-1, SOCS-1, and SOCS-3 genes." (PMID 33773553, 2021). "In the context of leukemia, SOCS1 methylation has been documented in a variety of leukemia subtypes, including about 60% of newly diagnosed AML." (PMID 34439155, 2021). "Based on our previous findings on SOCS1 in FLT3-ITD mediated leukemia we asked how SOCS family members are regulated by BCR-ABL expressing cells." (PMID 28753604, 2017). "When transplanted into mice, BCR-ABL and SOCS1/BCR-ABL induced leukemia with massive infiltration of hematopoietic tissues with differentiated myeloid cells." (PMID 28753604, 2017). "Socs1 expression is relevant to this as since in a retroviral model it was shown to significantly accelerate the FLT3ITD myeloproliferative phenotype or leads to leukemia." (PMID 36739348, 2023). "The restoration of SHP-1, SOCS-1, and SOCS-3 expression by epigenetic modulating agents such as 5-azacytidine (5-Aza) was associated with significant inhibition of JAK2/STAT3 and STAT5 signaling in AML leukemia cells." (PMID 34959687, 2021). "In these animals the presence of SOCS1 seemed to entirely protect from BCR-ABL mediated leukemia." (PMID 28753604, 2017). "A more profound understanding for the cytokine environment of leukemic cells and for the function of SOCS1 as an oncogene or as a tumor suppressor in BCR-ABL mediated transformation might be required to completely eradicate leukemia-initiating cells." (PMID 28753604, 2017). "Our results showed that DNA methylation of SOCS1 gene was a protective factor for leukemia." (PMID 24810788, 2014). "Treatment with this compound increases the levels of SOCS1 and SOCS3 in myeloproliferative neoplasms (MPNs) and leukemia." (PMID 35611249, 2022). "Validating the results showing upregulated gene expression, we observed an increase in the expression of SOCS1 and SOCS3 proteins in leukemia cells from PDX-1, PDX-2, Mutz-5, and Call-4." (PMID 36613920, 2022). "In this study, the authors examined the effects of TQ on the expression of JAK/STAT-negative regulator genes SOCS-1, SOCS-3, and SHP-1, and their consequences on cell proliferation and apoptosis in HL60 leukemia cells." (PMID 33773553, 2021). "SOCS-1 and SOCS-3 genes are also negative regulators of JAK/STAT pathway, were down-regulated in MV4-11 leukemia cells and their re-expression by demethylation was associated with inhibition of JAK/STAT signaling and lower cell proliferation." (PMID 33773553, 2021). "Furthermore, sodium butyrate treatment increases the transcript levels of SOCS1 and SOCS3 and inhibits cell proliferation in myeloproliferative neoplasms (MPNs) and leukemia." (PMID 35611249, 2022).
leukemia (continued). "Additionally, the expression of JAK/STAT-negative regulator genes, SHP-1, SOCS-1, and SOCS-3 genes, was investigated before and after treating HL60 leukemia cells with TQ." (PMID 33773553, 2021). "As expected, mock and SOCS1 transplanted animals did not develop leukemia." (PMID 28753604, 2017).
psoriasis (25 papers, 2015 to 2024). An autoimmune condition characterized by red, well-delineated plaques with silvery scales that are usually on the extensor surfaces and scalp. "Other genetic variants related to IL-23 and psoriasis risk include suppressor of cytokine signaling 1 (SOCS1) and ETS Proto-Oncogen 1 (ETS1)." (PMID 38256115, 2024). "In parallel, dysregulation of SOCS1 in psoriasis has been associated with enhanced dendritic cell activation, resulting in an increase of autoreactive T-cell priming s and perpetuation of the immune cascades." (PMID 38975347, 2024). "Among them, rs4780355 and rs33989964 single-nucleotide polymorphism (SNP) in SOCS1 associate with psoriasis and asthma conditions, respectively." (PMID 38975347, 2024). "Other genetic variants associated with psoriasis and related to IL-23 correspond to SOCS1 (coding for a suppressor of cytokine signal involved in Th17 differentiation) and ETS1 (coding ETS protooncogene 1 protein, involved in the negative regulation of Th17 differentiation)." (PMID 37628670, 2023). "Furthermore, our results show that the genes mediating the development of IBD in psoriasis may be associated with the following genes CSF2RA/SOCS1/PTPN2/STAT3/IL21R, which has implications for the exploration of co-morbid targets in PsO combined with IBD." (PMID 38803495, 2024). "In fact, while Sp1 and IRF-1 transcription activators of SOCS1 are expressed at similar levels in keratinocytes of healthy and psoriasis donors, the transcriptional repressors of SOCS1, the GFI-1b and KLF4, are downregulated in psoriatic cells." (PMID 38975347, 2024). "We additionally examined the protein levels of CDKN2B and SOCS1, the two target genes responsible for the effects of miR-17-92 cluster on keratinocytes, in the skin specimens from five psoriasis patients and five healthy controls using immunofluorescence." (PMID 29752469, 2018). "In psoriasis, the diminished expression of SOCS1 in T cells would contribute to the sustained activation of IL-23-driven pathways and differentiation of Th17 lymphocytes, thus fostering an environment conducive to chronic inflammation and aberrant keratinocyte proliferation." (PMID 38975347, 2024). "Several recently identified single-nucleotide polymorphisms (SNPs) that are linked to psoriasis susceptibility are found adjacent or in close proximity to genes associated with the innate immune response, such as IFIH1 (MDA5), NFKBIA, STAT3, and SOCS1." (PMID 25658361, 2015). "Interestingly, keratinocytes of psoriasis skin express increased levels of SOCS1, as compared to healthy cells, as consequence of an unbalanced binding of transcriptional activators and repressors to SOCS1 promoter after IFN-γ stimulation." (PMID 38975347, 2024). "In psoriasis, SOCS3 and SOCS1 suppress cytokine-induced apoptosis by sustaining the activation of the PI3K/AKT pathway in keratinocytes." (PMID 38975347, 2024). "IFN-γ/TNF-α-treated keratinocytes of psoriasis patients strongly express SOCS3 and SOCS1, at higher levels as compared to healthy cells." (PMID 38975347, 2024). "SOCS1 and SOCS3 expression is reduced in tumor lesions of BCC and SCC, as compared to other skin inflammatory conditions such as psoriasis, despite the high number of IL-22-secreting tumor-infiltrating lymphocytes." (PMID 38975347, 2024). "Compared to the control group, the expression of SOCS1 and SOCS3 in psoriasis mice was significantly decreased (p < .05)." (PMID 36444619, 2022). "We found that SOCS3 and SOCS1 expression was reduced in vivo, in tumor lesions of BCC and SCC, as compared to other skin inflammatory conditions such as psoriasis, despite the high number of IL-22-secreting TILs." (PMID 28445952, 2017). "A SOCS1-mimetic peptide Tkip, which resembles the peptide sequence surrounding the JAK-binding sequence of SOCS1, and similar peptides has been shown to inhibit inflammatory diseases such as experimental psoriasis and lung inflammation." (PMID 38415248, 2024).
psoriasis (continued). "Similarly to SOCS1, SOCS3 is also upregulated in psoriasis epidermis, especially in areas close to CD3+ dermal infiltrate likely producing inflammatory cytokines." (PMID 38975347, 2024). "More than 4500 cases and 10,000 controls were investigated in GWAS, where 7 non-HLA susceptibility loci shared by CD and psoriasis (9p24 near JAK2, 10q22 at ZMIZ1, 11q13 near PRDX5, 16p13 near SOCS1, 19p13 near FUT2, 17q21 at STAT3, 22q11 at YDJC) were found." (PMID 36443384, 2022). "Additionally, etanercept inhibited the activation of JAK/STAT3 signaling pathway and promoted the protein expression of SOCS1 and SOCS3 in psoriasis mice." (PMID 36444619, 2022). "Therefore, SOCS1/3, which is known as a potential blocker of the JAK pathway, attenuates the proliferation of keratinocytes in psoriasis." (PMID 36077239, 2022). "Similar to other related immune-mediated skin disorders, such as psoriasis, the miRNA17-92a-1 cluster promotes chemokines, such as CXCL9 and CXCL10, in keratinocytes and further T cell chemotaxis by inhibiting the expression of suppressor of cytokine signaling 1 (SOCS1)." (PMID 35328059, 2022). "Accordingly, our group recently developed a SOCS1-KIR mimetic, named PS-5, that significantly blocked IFN-γ-induced Jak2 and STAT1α activation, as well as expression of immunomodulatory molecules and chemokines in in vitro and ex-vivo experimental models of psoriasis." (PMID 28445952, 2017). "Not surprisingly, the expression of SOCS1 showed elevation in psoriatic epidermis, probably because cytokines-induced SOCS1 upregulation could not be completely reversed by miR-17-92 elevation in psoriasis lesions." (PMID 29752469, 2018). "However, the activation of SOCS1 and SOCS3 appears inadequate to completely inhibit the expression of STAT-downstream targets in psoriasis, making this negative circuit nonfunctional in the context of psoriasis, and it was, therefore, removed from the model." (PMID 34877506, 2021). "Neither JAK2 phosphorylation nor SOCS1 and SOCS3 expression was affected by HCA, suggesting that HCA-mediated suppression of PKM2-STAT3 signaling is a key event in the attenuation of psoriasis development." (PMID 33990689, 2021).
renal fibrosis (25 papers, 2017 to 2025). A final common manifestation of a wide variety of chronic kidney diseases characterized by glomerulosclerosis and tubulointerstitial fibrosis. "Chronic treatment with silymarin nanoliposomes effectively ameliorated inflammation, OS, and renal fibrosis via inhibiting JAK2/STAT3/suppressor of cytokine signaling 1 and TGF‐β/Smad signaling pathways in diabetic rats with STZ‐induced kidney injury." (PMID 41019174, 2025). "Researchers demonstrated that miR-155 and SOCS1 form a mutual feedback loop, increased miR-155 reduces SOCS1 expression, and diminished SOCS1 further augments miR-155 transcription, creating an amplification circuit that aggravates renal fibrosis." (PMID 41516293, 2025). "Upregulation of miR-155-5p is also reported to induce renal fibrosis by targeting suppressor of cytokine signaling 1 (SOCS1) and 6 (SOCS6)." (PMID 37505742, 2023). "One study showed that miR-150 antagonist induced an increase in markers of renal fibrosis (e.g., α-SMA, FN, and COL-1) in ICR mice, and this inducement was associated with the regulation of the SOCS1/JAK/STAT pathway, which is downstream of miR-150." (PMID 37635867, 2023). "It has been reported that miR-150 promotes renal fibrosis of lupus nephritis by downregulating the expression of SOCS1 in cultured kidney cells." (PMID 35990680, 2022). "The production of exosomes that contain miR-150-5p was observed to increase under hypoxic conditions in vivo, promoting fibroblast activation by targeting suppressor of cytokine signaling 1 (SOCS1) in vitro, leading to renal fibrosis." (PMID 36105281, 2022). "In mechanism, our data demonstrate that miR-155-5p promotes renal fibrosis by increasing the phosphorylated activation of STAT3 via targeting SOCS1/6." (PMID 32587662, 2020). "miR-150 promotes renal fibrosis in lupus nephritis by downregulating suppressor of cytokine signaling 1 (SOCS1), which leads to increased expression of profibrotic molecules in renal tissue." (PMID 31608058, 2019). "In a study that examined the expression of miR-150 in kidney biopsies obtained from patients with lupus nephritis, miR-150 was found to promote renal fibrosis, which was probably induced by increasing profibrotic molecules through the downregulation of SOCS1." (PMID 31218232, 2019). "MiRNAs affect renal fibrosis in kidney disease, among which miR-150 promotes renal fibrosis through down-regulating SOCS1." (PMID 29532746, 2018). "SOCS1 participates in renal fibrosis by downregulating JAK2/STAT1-mediated cytokine signaling in LN." (PMID 30214448, 2018). "It has been known that anti-dsDNA IgG participates in the processes of renal fibrosis through blocking the suppressor of cytokine signaling 1 signals and inducing fibronectin secretion or myofibroblast-like phenotype of renal resident cells." (PMID 30648117, 2018). "Suppressor of cytokine signaling 1 (SOCS1) participates in renal fibrosis by downregulating Janus kinase 2 (JAK2)/signal transducer and activator of transcription 1 (STAT1)-mediated cytokine signaling." (PMID 28620377, 2017). "The purpose of this study was to investigate the potential effect of anti-dsDNA IgG on the regulation of SOCS1 signals and also the molecular mechanism underlying SOCS1-KIR and JAK2/STAT1 interaction in the pathogenesis of renal fibrosis." (PMID 28620377, 2017). "Thus, the SOCS1/p-JAK1/p-STAT1 pathway contributes to renal fibrosis in folic acid-induced RIF mice." (PMID 35990680, 2022). "hsa-mir-155-5p can also regulate the pathogenesis of renal fibrosis via targeting SOCS1 and SOCS6." (PMID 35755170, 2022). "SOCS1 is downregulated in epithelial cells and fibroblasts involved in renal fibrosis." (PMID 34671216, 2021). "To further investigate the underlying mechanisms by which miR-155-5p involved in the pathogenesis of renal fibrosis, we identified SOCS1/6 as its putative targets using bioinformatics tools, and these results were experimentally validated in NRK-49F and HK-2 cells and clinical specimens." (PMID 32587662, 2020).
renal fibrosis (continued). "A previous study reported that renal miR-150 could upregulate profibrotic molecules by downregulating the expression of the antifibrotic protein suppressor of cytokine signaling 1 (SOCS1) to promote renal fibrosis." (PMID 31001261, 2019). "Additionally, anti-dsDNA IgG contributes to renal fibrosis through selective inhibition of the suppressor of cytokine signaling 1 signals." (PMID 30648117, 2018). "Therefore, anti-dsDNA IgG participates in renal fibrosis of LN by suppressing SOCS1 signals, and DNA-mimicking peptide can restore such SOCS1 inhibitory effect and ameliorate renal fibrosis." (PMID 28620377, 2017). "Currently, SOCS1 has been proven to be an inhibitor of renal fibrosis." (PMID 28620377, 2017). "Furthermore, three miRNAs have been associated with renal fibrosis in LN patients: miR-410, which contributes to renal fibrosis by inhibiting interleukin-6, miR-29c as predictor of early renal fibrosis, and miR-150, which promotes renal fibrosis by downregulation of SOCS1." (PMID 31349698, 2019). "Therefore, anti-dsDNA IgG suppresses SOCS1 signals and contributes to renal fibrosis." (PMID 28620377, 2017). "In conclusion, anti-dsDNA IgG downregulates SOCS1 expression, activates JAK2/STAT1 signals, and contributes to renal fibrosis; its peptide blockade may restore the SOCS1 inhibitory effect on the production of profibrotic cytokine, and finally ameliorate renal fibrosis in LN." (PMID 28620377, 2017). "Renal delivery of SOCS1 and SOCS3 alleviated proteinuria, reduced OSM expression and ECM deposition, partially restored the expression of CK18 and α-SMA, and improved renal fibrosis in the kidneys of diabetic CD-1 mice." (PMID 37635867, 2023). "We further investigated the effects of LNA-anti-miR-150 on SOCS1/JAK/STAT and the infiltration of macrophages, including M1 and M2 subtypes, in folic acid-induced renal fibrosis mice." (PMID 35990680, 2022). "SOCS1 is also involved in other pathological processes of SLE including activation of immune cells, production of proinflammatory factors, initiation of renal fibrosis, etc.." (PMID 29085365, 2017). "However, the relationship between the SOCS1/JAK/STAT pathway and M2 macrophages in renal fibrosis remains unclear." (PMID 35990680, 2022).
multiple myeloma (24 papers, 2008 to 2024). "SOCS proteins mediate inhibition of the STAT pathways, and downregulation of SOCS1 is frequent in multiple myeloma." (PMID 24416592, 2013). "miR-19a has been shown to regulate SOCS1 expression during mutiple myeloma and be induced by the anti-viral cytokine interferon-(IFN)-α, suggesting a role in the regulation of the JAK-STAT pathway." (PMID 23894411, 2013). "Interestingly, miR-19a is induced by the anti-viral JAK-STAT signalling cytokine, IFN-α and reduces SOCS1 expression, which may be linked to enhanced IL-6 signalling in multiple myeloma, suggesting a significant role for miR-19a in the regulation of the JAK-STAT pathway." (PMID 23894411, 2013). "High expression of both miR-19a and miR-19b, members of the miR-17-92 cluster, also targets SOCS1 in myeloma cells." (PMID 24416592, 2013). "It has been demonstrated that it acts as a positive regulator of antiapoptotic Stat3/IL-6 receptor signaling by directly suppressing SOCS-1, thereby facilitating malignant growth of multiple myeloma." (PMID 20868483, 2010). "SOCS1 modulates the interaction between tumor and bone marrow accessory cells in multiple myelomas." (PMID 28968979, 2017). "The regulation of SOCS1 by miR-19 has been reported in mutiple myeloma cells." (PMID 23894411, 2013). "Moreover, miR19a/b downregulated SOCS1 expression in multiple myeloma cell lines in vitro." (PMID 34439155, 2021). "In multiple myeloma (MM), a cancer affecting plasma cells, several tumor suppressor genes (e.g., CDKN2A, CDKN2B, SOCS1, and SHP1) are hypermethylated in the CpG islands of their promoters, leading to gene translation inhibition." (PMID 38248418, 2024). "miR-19a is a member of the miR-17-92 cluster and has been shown to be overexpressed in T-cell acute lymphoblastic leukemia and multiple myeloma where it was revealed that miR-19a negatively regulates the expression of CYLD and SOCS-1 respectively to promote cell survival and pathogenesis." (PMID 25886994, 2015). "SOCS1 may bind to the JAK2 kinase SH2 domain, inhibiting its activity, and is also a negative regulator of IL-6; therefore, it may function as a tumor suppressor in multiple myeloma." (PMID 37514090, 2023). "However, SOCS-1 gene methylation is frequent but does not appear to have prognostic value in patients with multiple myeloma." (PMID 28915645, 2017).